MIR4498 (microRNA 4498)
Synonyms: hsa-mir-4498; mir-4498
Gene: MicroRNA gene on chromosome 12 (120,155,434 to 120,155,499, reverse strand). Ensembl gene ENSG00000266704.
Homologues: Orthologues: chimpanzee MIR4498 (100% identical).